TRPV1 (transient receptor potential cation channel subfamily V member 1)
Diseases named in the same sentence as TRPV1 in open-access papers (continued):
Sharing a sentence is not in itself a finding about the gene and the disease.
epilepsy (continued). "Regarding genetically epilepsy-prone rats (GEPR-3s), CPZ (a TRPV1 antagonist) reduced seizure severity in a dose-dependent manner in male rats and in female rats CPZ suppressed seizure susceptibility." (PMID 33202963, 2020). "Another elegant confirmation of the link between epilepsy and TRPV1 was observed in animals lacking TRPV1 (knock-out)." (PMID 38404644, 2024). "Reports showed that TRPV1 channel activation enhanced glutamate release and glutaminergic signaling, decreased GABA release, and induced Ca2+ accumulation, which were confirmed to be responsible for synaptic efficacy and epilepsy." (PMID 34925021, 2021). "TRPC1, TRPC3-7, TRPM2, TRPM7, TRPV1, TRPV4, and TRPA1 have been shown to be involved in epilepsy." (PMID 33748103, 2021). "Notably, the interaction between TRPV1 and CB1 receptors is crucial for the pharmacodynamics of cannabidiol, which is currently used in children with pharmacoresistant epilepsy, such as Dravet or Lennox–Gastaut syndromes." (PMID 31486023, 2020). "Collectively, TRPV1 promoted astrocyte migration thus helped the infiltration of pro-inflammatory cytokines (TNF, IL-1β, IL-6, and iNOS) from astrocytes into the vicinity of neurons to promote epilepsy." (PMID 31722723, 2019). "Specifically, TRPV1 translocated to the astrocytic membrane after HIBD, promoting astrocyte migration and inflammatory infiltration, thereby increasing neuronal excitability and promoting the onset of epilepsy." (PMID 31722723, 2019). "This hypothesis is supported by recent studies, which showed that TrpV1 expression is increased in hippocampal CA1 and CA3 pyramidal neurons of a rat model of epilepsy." (PMID 30417826, 2018). "The effectiveness of TRPV1 antagonists should be studied with caution, as there are no chronic studies that show pharmacokinetic profile, efficacy and tolerability in preclinical models of epilepsy." (PMID 33202963, 2020). "However, the detailed mechanism of astrocytic TRPV1 in epilepsy after HIBD has not been fully elucidated." (PMID 31722723, 2019). "Our data revealed the role of TRPV1 channels in seizure generation after HIBD, which may be a promising way to develop an effective immune therapy, such as broadening anti-inflammatory drug screening and designing clinical strategies for HIBD-induced epilepsy." (PMID 31722723, 2019). "However, whether targeting Trpv1 is anticonvulsant in animal models of drug-resistant epilepsies is not known." (PMID 34079465, 2021).
osteoarthritis (41 papers, 2010 to 2026). A noninflammatory degenerative joint disease occurring chiefly in older persons, characterized by degeneration of the articular cartilage, hypertrophy of bone at the margins and changes in the synovial membrane. "Clinical trials also show promising effects following the injection of either a prodrug of capsaicin at the site of surgery for the control of post-operative pain, or the ultra-potent TRPV1-agonist resiniferatoxin in joints for the treatment of pain associated with osteoarthritis." (PMID 40283995, 2025). "Further, there is evidence of TRPV1 involvement in osteoarthritis patient populations, including a TRPV1 variant associated with increased knee osteoarthritis, and increased expression of TRPV1 in the knee synovium of patients with osteoarthritis." (PMID 27854251, 2016). "Therefore, future studies should investigate whether osteoarthritis pain and neuropathic pain are reduced through the inhibition of TRPV1 activity caused by naringin at a preclinical or clinical stage." (PMID 35052566, 2021). "TRPV1 sensitization may be involved in chronic pain caused by osteoarthritis." (PMID 33036283, 2020). "As capsaicinoids bind and activate the transient receptor potential vanilloid 1 (TRPV1) receptor, it is also plausible that the observed effects involve TRPV1-mediated Ca2+/CaMKII/Nrf2 signaling, as reported in osteoarthritis models." (PMID 40430052, 2025). "Transient receptor potential vanilloid family member 1 (TRPV1) has been revealed as a therapeutic target of osteoarthritis (OA), the most common deteriorating whole joint disease, by impeding macrophagic inflammation and chondrocytes ferroptosis." (PMID 38371274, 2024). "This study aims to determine the molecular mechanisms and analgesic effects of transient receptor potential vanilloid 1 (TRPV1) in the treatments of osteoarthritis (OA) and rheumatoid arthritis (RA)." (PMID 37994506, 2024). "Throughout the pathological progression of osteoarthritis, the release of inflammatory factors activates TRPV1 channels, thereby triggering an increase in neuronal excitability and intensifying the transmission of pain signals." (PMID 38540712, 2024). "In osteoarthritis, TRPV1 primarily expressed in sensory neurons contributes to pain perception and transmission." (PMID 38540712, 2024). "We search and analyse the related literature in Google Scholar, Web of Science and PubMed databases from inception to September 2023 through the multi‐combination of keywords like ‘TRPV1’, ‘ion channel’, ‘osteoarthritis’, ‘rheumatoid arthritis’ and ‘pain’." (PMID 37994506, 2024). "Targeting the TRPV1 channel pathway to alleviate osteoarthritis pain is effective based on the current data." (PMID 38235147, 2023). "Intra-articular treatment with resiniferatoxin, another agonist of TRPV1 led to reduced pain in the induced osteoarthritis model." (PMID 38235147, 2023). "Blockage of TRPV1 led to significant inhibition of joint pain and proved to be a promising therapeutic against osteoarthritis." (PMID 38235147, 2023). "In macrophages TRPV1 inhibits M1 polarization via Ca2+/CaMKII/Nrf2 signalling pathway and influences cytokine production in models of osteoarthritis, sepsis, inflammatory tissue fibrosis and viral infection." (PMID 36160429, 2022). "Two-stage experiments revealed the effective inhibition of TRPV1 in the management of osteoarthritis knee pain." (PMID 35052566, 2021). "The potential use of resiniferatoxin, currently in clinical trials for cancer and osteoarthritis pain, as a possible ablating agent of TRPV-1 positive pulmonary pathways in patients with advanced COVID-19 disease, was recommended." (PMID 34805220, 2021). "Based on our previous paper assessing the role of the TRPV1 receptor in osteoarthritis, we decided to evaluate the expression of TRPV1-sensitizing factors in the lumbar spinal cord." (PMID 34681188, 2021).
osteoarthritis (continued). "Future studies in this area will not only be beneficial to horses and their owners, but more knowledge about TRPV1, the mode of action, and possible side effects will also benefit translation into human osteoarthritis research." (PMID 32197454, 2020). "Transient receptor potential vanilloid 1 (TRPV1)—also known as the ‘chili receptor’—is currently being investigated as a target for treating osteoarthritis in humans." (PMID 32197454, 2020). "In humans, antagonists of TRPV1 channels are being studied in clinical trials on osteoarthritis and atopic dermatosis, conditions where there is a pH imbalance." (PMID 30194289, 2018). "Contrarily, clinical development of a TRPV1 agonist, zucapsaicin, has been successful, and is currently in clinical use for osteoarthritis." (PMID 27854251, 2016). "Based on these pre-clinical findings, several small molecule antagonists of nociceptive TRP channels, mainly targeting TRPV1, have been tested in clinical trials for multiple inflammatory pain conditions, such as dental pain and osteoarthritis." (PMID 27854251, 2016). "In a rat model of osteoarthritis the intraarticular injection of the TRPV1 antagonist JNJ17203212 almost completely eliminated the weight bearing asymmetry in mice." (PMID 27563913, 2016). "These researchers also studied the importance of CNS exposure and the role of central TRPV1 actions in the MIA osteoarthritis model." (PMID 24288084, 2012). "Preclinical localization and expression studies provide a firm foundation for the use of molecules targeting TRPV1 for conditions of bone pain, osteoarthritis and neuropathic pain." (PMID 24288084, 2012). "Therefore, the mechanisms of TRPV1 in osteoarthritis encompass its distribution within the nervous system and its intricate regulatory role in pain transmission and inflammatory responses." (PMID 38540712, 2024). "Furthermore, animal and human studies showed that TRPV1+ neurons generate nociceptive signals from many tissue damage conditions, including noxious heat, cancer, osteoarthritis, surgical incision, inflammation, and other stimuli." (PMID 38261410, 2024). "Also, TRPV1 is known to be stimulated by several inflammatory neuropeptides and signaling molecules and overexpressed in osteoarthritis; thus, it is reasonable to expect a similar pattern of expression in specimens retrieved from patients affected by CLBP." (PMID 32955611, 2021). "To evaluate whether it could be a potential target in treating osteoarthritis in horses, we collected synovial membrane samples from healthy horse joints and horse joints with joint disease to investigate the expression of the TRPV1." (PMID 32197454, 2020). "It will also be important to assess the side effect and adverse effect profile of Myrcene and to assign its documented effects in pain and other potential indications (ischemia/reperfusion injury, osteoarthritis, peptic ulcer, anti-oxidant) to TRPV1 or other possible receptors." (PMID 31446830, 2019). "Indeed, it has recently been shown that intra-articular administration of a TRPV1 antagonist attenuated early osteoarthritic pain in a mono-sodium iodoacetate model of osteoarthritis." (PMID 30240782, 2018). "In osteoarthritis models, both TRPV1 and TRPA1 have been shown to play an important role." (PMID 27854251, 2016). "In a phase II clinical trial, the TRPV1 antagonist AZD1386 failed to cause significant pain relief in patients with osteoarthritis, suggesting a more complex role for TRPV1, as well as involvement of other nociceptive channels/receptors in osteoarthritis." (PMID 27854251, 2016). "However, in humans, TRP antagonists mainly targeting TRPV1 have been tested for conditions such as dental pain and osteoarthritis, but have shown adverse effects (mainly body temperature dysregulation—hyperthermia), which contributed to the termination of clinical trials." (PMID 32824721, 2020). "This means that TRPV1 could be used as a potential target for osteoarthritis treatment in horses." (PMID 32197454, 2020).
osteoarthritis (continued). "The validity of the idea that TRPV1 activation generates ROS was also tested using human primary synoviocyte cultures harvested from clinical synovial fluid samples drawn from the knee joints of patients with active arthropathies (osteoarthritis and acute pseudogout)." (PMID 20691059, 2010). "To date, TRPV1 agonist, capsaicin or resiniferatoxin, and antagonists such as capsazepine (CPZ), BCTC, SB-705498, or NEO6860 were tested to treat migraine, osteoarthritis, overactive bladder, atopic dermatitis, and neuropathic pain (clinicaltrials.gov)." (PMID 31681615, 2019). "In animal models both TRPV1 and TRPA1 activation results in increased release of TNF-α, a pro-inflammatory cytokine important for the development of osteoarthritis." (PMID 27854251, 2016). "PGE2/EP4 pathway-induced activation of the transient receptor potential cation channel subfamily V member 1 (TRPV1) may be another subchondral bone homeostasis and osteoarthritis pain mechanism." (PMID 36078169, 2022). "The exception was represented by patient 6, in whom the expression of TRPV4 and TRPM8 channels was similar to control tissue and TRPA1, TRPV1, and TRPV2 were expressed, although at a lower level, also in the tissue used as control (probably due to an initial degree of osteoarthritis in this tissue)." (PMID 32955611, 2021). "The peripherally restricted TRPV1 antagonist, A-425619, has been previously shown to reverse thermal and mechanical hypersensitivity in rat CFA models and also restore weight bearing ability in rat osteoarthritis models." (PMID 30240782, 2018). "Additionally, in the mono-iodoacetate (MIA) model of osteoarthritis, joint afferents in the DRG, as determined by Fast Blue staining, expressed a greater amount of TRPV1 (72%) compared to normal joint afferents (54%)." (PMID 24288084, 2012). "In patients with osteoarthritis, TRPV1 is expressed on synovium, as well as synovial fibroblasts suggesting both a neuronal and a non-neuronal role of TRPV1 in this condition." (PMID 24288084, 2012). "A different TRPV1 antagonist ABT-116, however induced only moderate pain relief in dogs in an experimental model of synovitis, and a third TRPV1 antagonist AZD1386 was withdrawn from clinical trials because of the absence of significant clinical benefit in osteoarthritis patients." (PMID 27563913, 2016).
atopic dermatitis (36 papers, 2014 to 2026). "These interleukins are known to be associated with pruritic disorders such as atopic dermatitis and allergic contact dermatitis, thus highlighting the role of TRPV1 channels in these conditions." (PMID 36613861, 2022). "This confirms the possibility of using TRPV1 antagonists in the treatment of skin conditions such as pruritus associated with atopic dermatitis." (PMID 31681615, 2019). "In this context, another notable TRPV1 inhibitor is asivatrep, a selective agent that has been shown to effectively alleviate pruritus in patients with atopic dermatitis." (PMID 41222137, 2025). "Recently, studies have demonstrated a close relationship between TRPV1 and pathogenesis of both psoriasis and allergic dermatitis." (PMID 41226679, 2025). "Recently, an increase in TRPV1 expression in skin nerve fibers has been observed in atopic dermatitis induced with trinitrochlorobenzene in Nc/Nga Mice." (PMID 40095628, 2025). "In clinical practice, this suggests potential as a therapeutic option for conditions driven by TRPV1 overactivation, such as atopic dermatitis and rosacea." (PMID 41222137, 2025). "We measured Transient Receptor Potential Vanilloid 1 (TRPV1) expression levels through immunofluorescent staining in skin tissue from both atopic dermatitis patients and the MC903-treated mice." (PMID 39257398, 2024). "Since we showed that AD-related cytokines upregulate TRPV1 surface expression on human peripheral blood eosinophils, we investigated TRPV1 expression in symptomatic skin of atopic dermatitis patients (n = 3) by staining skin sections." (PMID 38339203, 2024). "In this model of atopic dermatitis, cysteine protease activity within house dust mite extracts was necessary for sensitizing TRPV1+ neurons." (PMID 39493768, 2024). "The hope is that ongoing research on Asivatrep or other topical TRPV1 blockers advances not only in addressing atopic dermatitis but also in proving effective against the venomous effects of caterpillars." (PMID 38940922, 2024). "Consistent with this proposal has been the demonstration that TRPV1+/SP+ nociceptor–MRGPRB2 mast cell clusters are critical in driving the clinical score of a severe preclinical model of atopic dermatitis." (PMID 39493768, 2024). "A clinical trial showed that topical application of Asivatrep cream (TRPV1 antagonist) improved clinical signs and symptoms of atopic dermatitis." (PMID 36919561, 2023). "In contrast, in skin biopsies from patients with atopic dermatitis, TRPV1 and TRPV2 were upregulated and TRPV3 and TRPM8 were downregulated." (PMID 36552866, 2022). "In other pruritic dermatoses, such as psoriasis and atopic dermatitis, increased TRPV1 expression on nerve fibers and subsequent release of CGRP are the mainstream causes of the vicious pro-itch cytokine cycle." (PMID 36551194, 2022). "Increased expression and phosphorylation of TRPV1 has also been observed in atopic dermatitis lesions." (PMID 36613861, 2022). "A phase III randomized controlled trial recently evaluated the use of Asivatrep, a topical TRPV1 antagonist, for the treatment of atopic dermatitis." (PMID 36613861, 2022). "Administration of a topical TRPV1 antagonist markedly reduced scratching behavior, as well as erythema and edema, in atopic dermatitis mice models by day 12 of treatment, a finding previously supported by other murine studies." (PMID 36613861, 2022). "TRPV1 antagonists and TRPV1 pathway antagonists have been used or are currently in clinical trials to treat atopic dermatitis (AD) and psoriasis." (PMID 34200205, 2021). "Both PAR2 and TRPV1 were shown to be upregulated in the skin of patients with atopic dermatitis and in mouse models for atopic dermatitis." (PMID 33791327, 2021). "In the case of TRPV1, blockade of activation using a TRPV1 antagonist compound can suppress atopic dermatitis-like symptoms by accelerating skin barrier recovery in atopic dermatitis murine models." (PMID 32054030, 2020).